FABP4 (fatty acid binding protein 4)
Diseases named in the same sentence as FABP4 in open-access papers (continued):
Sharing a sentence is not in itself a finding about the gene and the disease.
Obesity (continued). "The observed lower expression of genes such as CD36 and FABP4 in melanoma may reduce the cellular internalization of fat and therefore make patients with melanoma less sensitive to a high dietary fat intake, explaining in part the obesity paradox observed in patients with melanoma." (PMID 32209538, 2020). "Lipid accumulation plays an important role in the development of obesity and is regulated by various adipogenic-specific proteins including SREBP-1c, PPARγ, and C/EBPα, as well as lipogenic enzymes such as FABP4 and FAS." (PMID 31717668, 2019). "In fact, a large number of studies have shown that plasma levels of FABP4 are increased in obesity and T2DM, and that circulating FABP4 concentration correlated with clinical outcomes, such as body mass index, insulin resistance, and dyslipidemia." (PMID 30857223, 2019). "In the obesity model, PPARγ, C/EBPα, STREBP-1c, ACC, FABP4, FAS, and HSL were increased while PLIN was decreased in WAT." (PMID 31533255, 2019). "Undoubtedly, the role of FABP4, sCD36, and RBP4 as the potential biomarkers of obesity, metabolic syndrome, and cardiovascular diseases was also confirmed in our studies." (PMID 29335416, 2018). "Fatty acid binding protein 4 (FABP4) is an abundant protein in adipocytes, and its production is influenced by high-fat diet (HFD) or obesity." (PMID 29340091, 2017). "It has been proposed that under pathological conditions (e.g., obesity), coincident CD45/FABP4 ring staining occurs that is due to a crown of macrophages surrounding necrotic adipocytes." (PMID 28420992, 2017). "However, most studies regarding the association between Fabp4 and obesity/IR have focused on the serum or adipocyte rather than skeletal muscle Fabp4; the exact mechanisms by which Fabp4 regulates different biological functions in skeletal muscle are not well understood." (PMID 23326526, 2013). "The aim of this study was to analyze the FABP4 expression in paired samples of SAT and VAT and hepatic tissues in the context of obesity and IR in patients with a wide BMI range." (PMID 23139800, 2012). "Our results indicate that the greater the degree of obesity the lower the gene expression of genes related with lipid processing in adipose tissue (LPL, FABP4, ASP and LRP1), both visceral and subcutaneous, though more obviously in the VAT." (PMID 21966368, 2011). "Here, we discuss the molecular and cellular basis of the roles of FABPs, especially FABP4 and FABP5, in metaflammation and related diseases including obesity, diabetes, and atherosclerosis." (PMID 22121495, 2011). "Although further studies are still needed, reducing the levels of apoC-III, FABP4 and liver fat would prevent the changes in HDL component and help to ameliorate HDL-C metabolism, especially in obesity and insulin resistance." (PMID 21988829, 2011). "These contrasting findings suggest that FABP4 may exert tumour-suppressive effects in general HCC, but facilitate tumour progression in obesity-related HCC, highlighting its context-dependent function." (PMID 41149452, 2025). "Significant lipid accumulation in the uterine smooth muscle, with lipids stored as droplets within cells, inhibited myometrial contractions, indicating that elevated FABP4 directly impairs uterine contractions independent of obesity or HFD." (PMID 40192565, 2025). "Elevated FABP4 levels drive lipid accumulation, weaken MAMs coupling, and impair uterine contractions, independent of obesity." (PMID 40192565, 2025). "Mice overexpressing the Wnt ligand Wnt10b in adipocytes from the FABP4/aP2 promoter were shown to have impaired WAT (and BAT) development, with a reduction in the number but not in the size of adipocytes and protection from dietary and genetic obesity." (PMID 38727299, 2024). "We analyzed the levels of these adipokines based on BMI and identified an obesity effect on leptin and IL-6 but not adiponectin and FABP4." (PMID 39408921, 2024).
Obesity (continued). "The excessive or absent expression of FABP4 has been demonstrated to play a role in various aspects of metabolic disorders and resulting negative consequences, including dyslipidemia, obesity, metabolic syndrome and atherosclerosis." (PMID 39527497, 2024). "Despite FABP4 serum levels not being determined in our study, here we report a novel association between circulating TG and its expression in SAT in obesity." (PMID 36769659, 2023). "FABP4 mRNA levels were also quantified in SAT samples from 21 normotriglyceridemic subjects without obesity (non-Ob)." (PMID 36769659, 2023). "In addition, PA‐induced high expression of the adipocyte obesity genes Leptin and FABP4, while BMSC‐Exos also significantly and dose‐dependently reduced Leptin and FABP4 protein levels." (PMID 37073893, 2023). "Obesity increases systemic levels as well as cellular secretion of many cytokines and adipokines including leptin, IL6, TNFα, IGF1, fatty acid binding protein 4 (FABP4), and resistin, which are all involved in regulating the pathways associated with the development of CSCs in breast cancer tissue." (PMID 36010901, 2022). "In addition, several novel adipokines have been identified, including FABP4, apelin, endotrophin, visfatin, lipocalin 2, osteopontin, ANGPTL2, omentin-1, and chemerin, the roles of which as mediators between obesity and cancer have also been reported." (PMID 36060264, 2022). "FABP4, also known as A-EABP, which is expressed predominantly in adipose tissue and macrophages, has become the most studied FABP family member because of its notable function in obesity-related diseases." (PMID 36060264, 2022). "SAT FABP4 mRNA level was decreased in CAD patients compared to NCAD individuals without respect to their obesity status (p=0.001)." (PMID 34609443, 2021). "Mice with diet or genetically induced obesity and lacking FABP4 have lower plasma glucose, triacylglycerol and cholesterol and better insulin sensitivity than control littermates." (PMID 34638803, 2021). "Animal studies reveal ideal response to FABP4 inhibitors in asthma, obesity, and type 2 diabetes mellitus without significant toxicity." (PMID 34685761, 2021). "In adipocytes, FABP4 activates hormone-sensitive lipase (HSL) to regulate lipolysis of adipocytes, and lipid metabolism disorder and chronic inflammatory response are two important characteristics of obesity." (PMID 31651326, 2019). "More recently, additional adipokines regulated by obesity have been isolated in the secretome from adipocytes, including fatty acid-binding protein 4 (FABP4), also known as adipocyte-type fatty acid binding protein (A-FABP)." (PMID 30575815, 2019). "Fabp4-/- mice do not weigh less than wildtype mice due to the compensatory upregulation of Fabp5 but they are protected from diet-induced obesity, obesity-induced insulin resistance, and hyperglycaemia." (PMID 31260507, 2019). "In fact, FABP4 and FABP5 have been involved in obesity, atherosclerosis, and metabolic disease." (PMID 30142969, 2018). "It has been reported that increased circulating FABP4 levels are associated with obesity, insulin resistance, T2DM, hypertension, breast cancer independent of obesity, cardiac dysfunction, atherosclerosis, and metabolic syndrome." (PMID 30513800, 2018). "In summary, FABP4 and FABP3 may play a pivotal role in numerous disorders, including obesity, atherosclerosis, MS, IR and CAD, which are closely associated with psoriasis." (PMID 27864793, 2017). "Moreover, FABP4 gene expression was negatively correlated with BW and fat mass, whereas LECT2 gene expression was positively correlated with obesity and insulin resistance." (PMID 28924246, 2017). "The FABP4 inhibitor, BMS309403, improved glucose metabolism and enhanced insulin sensitivity in both dietary (high fat-fed) and genetic (ob/ob) mouse models of obesity and diabetes." (PMID 22121495, 2011).
Obesity (continued). "A 10-year prospective study showed that high FABP4 concentration at baseline was a biomarker predicting development of type 2 diabetes, which was independent of obesity and insulin resistance." (PMID 22121495, 2011). "Furthermore there was no significant change in the mRNA expression over 48 hours of CD14, endothelin-1 or ACE while there was a marked decrease in FABP-4, GPX-3, and LPL mRNA but enhanced release in obesity." (PMID 20508843, 2010). "One innovative approach in obesity research involves using a nonviral, adipose tissue-targeted gene delivery system to guide a CRISPRi complex toward white adipocytes, aiming to silence fatty acid-binding protein 4 (Fabp4)—a key regulator of lipid handling." (PMID 41150735, 2025). "Notably, in AAV‐FABP4 mice fed an ND, ATP production was also reduced, indicating FABP4 directly impairs energy metabolism, independent of obesity or HFD." (PMID 40192565, 2025). "Compared with the observed substantial correlations of FABP-4 with BMI and waist circumference, the weak positive correlation of FABP-4 with ABSI, a measure that was designed as a body shape index independent of BMI, suggests that FABP-4 is particularly influenced by general obesity." (PMID 37833736, 2023). "Therefore, FABP4 is not the ideal candidate for noninvasive NASH diagnosis in patients with obesity." (PMID 36609276, 2023). "Therefore, the involvement of FABP4 was not “one-direction” or monotonous when trying to unravel the role of FABP4 in obesity-related carcinogenesis in either in vitro or in vivo studies." (PMID 36060264, 2022). "However, controls were selected randomly and we did not determine any relationship between obesity and FABP-4 levels." (PMID 34217172, 2021). "It has been determined that Lactobacillus kefiri DH5 exerts these anti-obesity effects by reducing cholesterol absorption in the intestinal lumen and increasing the expression of PPARα, carnitine palmitoyl transferase-I (CPT1), and fatty acid-binding protein 4 (FABP4) in adipose tissue." (PMID 34945650, 2021). "Indeed, in the context of dietary or genetic obesity in mice, the lack of FABP4 protects from the development of insulin resistance and type 2 diabetes, despite slightly higher body weight and elevated plasma free FA concentrations." (PMID 30691227, 2019). "Taken together, FABP4 may enhance PCa progression and invasiveness by upregulating matrix metalloproteinases and cytokine production in the PCa stromal microenvironment, especially under HFD or obesity." (PMID 29340091, 2017). "This implies that serum FABP4 is influenced by disease status rather than obesity." (PMID 29340091, 2017). "For example, in contrast with control mice, FABP4-deficient mice did not develop insulin resistance or diabetes in diet-induced obesity mode and Fabp4 mRNA expression in circulating leucocytes isolated from Apoe−/− (apolipoprotein E-null) mice was correlated with atherosclerotic lesion size." (PMID 26823558, 2016). "Hence, it is clear from the results that FABP4 level is not a marker differentiating CVD from obesity in the studied population." (PMID 23119072, 2012). "Furthermore, the roles of ENG, FABP4, and CADM1 in critical biological processes such as vascular function, lipid metabolism, immunity, and adipose tissue regulation highlight the complex, and to some extent distinct etiology of childhood obesity from that of obesity presenting later in life." (PMID 41398348, 2025). "Our results showed that the PPARγ, C/EBPα, FABP4, and FAS genes were significantly downregulated in CA-treated mice, suggesting that CA may have the ability to reduce lipid accumulation and further alleviate obesity by restraining adipogenesis and lipid synthesis." (PMID 36839338, 2023).
Obesity (continued). "Similarly, serum FABP4 levels were increased in patients with diabetes (non-DM: 25.20 ± 1.26 ng/mL; DM: 36.39 ± 1.82 ng/mL, P < 0.001), obesity (non-OB: 25.51 ± 1.40 ng/mL; OB: 41.24 ± 2.32 ng/mL, P < 0.01) and metabolic syndrome (non-MS: 20.39 ± 1.09 ng/mL; MS: 35.90 ± 1.59 ng/mL, P < 0.001)." (PMID 34966292, 2021). "Additionally, the down-regulation of FABP4 and CD36 transcripts with LOCK suggests that changes in PRAT following LOCK may mirror changes observed in obesity given findings that obese men display a down-regulated adipose tissue fatty acid trafficking transcriptomic signature compared to lean men." (PMID 26678390, 2015). "Independent of PPAR-γ regulation the modification of FABP4 function by specific antagonists, inhibitors of gene expression (for example microRNA), or neutralizing antibodies could be novel therapeutic approaches for treating diseases such as obesity, DM, cardiovascular disease, and atherosclerosis." (PMID 39599599, 2024). "A series of studies with mice lacking both FABP4 and FABP5 (double knockout (DKO) mice) provided evidence that FABP4/5 are involved in the development of metabolic diseases, including diet-induced obesity, type 2 diabetes and insulin resistance." (PMID 30866899, 2019). "Mice lacking both FABP4 and 5 (FABP−/− mice) are strongly protected from diet-induced obesity, insulin resistance, type-2 diabetes and liver steatosis." (PMID 21738729, 2011). "Nonetheless, considering high rates of postpartum obesity in WWH and without HIV in this setting, positive correlation between FABP4 and adiposity measures observed in this study may increase the risk of CVD." (PMID 40759955, 2025). "However, unlike ROS, vitexilactone did not promote the expression of FABP4, FAS (promoter of obesity), or ATGL (inducer of insulin resistance)." (PMID 29165364, 2017). "While our current study does not directly address the local effects of hepatic FABP4, we believe we have comprehensively demonstrated the impact of adipose tissue–derived FABP4 on HCC cells, providing insights into HCC pathogenesis, particularly within the context of obesity." (PMID 41392988, 2025). "However, a limitation of the study was not having carried out an assessment of the expression of obesity-related genes such as family peroxisome proliferator-activated receptor (PPAR), adipocyte fatty acid binding protein (AFABP, also known as aP2 and FABP4), and stearoyl-CoA desaturase (SCD)." (PMID 39408365, 2024). "Cells isolated from elderly subjects with or without obesity were significantly impaired in their capacity to differentiate into adipocytes, as revealed by Oil Red O staining of neutral lipids and by the gene expression of common adipogenic markers (PPARG, FABP4, LPL, PLIN1, and FASN)." (PMID 35811457, 2022). "Importantly, we demonstrated that upregulation of fatty acid-binding protein 4 (FABP4) by environmental stimuli (i.e., high-fat diet, obesity) upregulates DNMT1, but not DNMT3a and DNMT3b, partially through activation of the IL–6/STAT3 signaling in cell non-autonomous manner in leukemia cells." (PMID 34203568, 2021). "Combined with the conclusion of Maeda that the lack of both FABP4 and FABP5 has a stronger protective effect on diet-induced insulin resistance, obesity, and atherosclerosis than any single lack, so we speculated that silibinin may also affect lipid transport through FABP5." (PMID 32184719, 2020).
Insulin resistance (236 papers, 2010 to 2026). Increased resistance towards insulin, that is, diminished effectiveness of insulin in reducing blood glucose levels. "FABP4 is thought to contribute to insulin resistance, a feature of type II diabetes, with an association between the latter and high FABP4 concentrations." (PMID 40364401, 2025). "Research involving mice has shown that insulin resistance and diabetes improved when FABP4 was deficient, providing additional evidence to support the role of FABP4 in diabetes." (PMID 41471323, 2025). "FABP4 has been linked to the biological development of atherosclerosis by contributing to inflammation, insulin resistance, and other cardiovascular risk and has shown potential as a biomarker for diagnosing PAD in diabetic patients." (PMID 40278353, 2025). "FABP4 deficiency is a promising treatment for insulin resistance, dyslipidemia, atherosclerosis, and other metabolic illnesses." (PMID 38341383, 2024). "Aberrant circulatory FABP4 level is associated with insulin resistance, diabetes mellitus, gestational diabetes, and metabolic syndrome." (PMID 37794302, 2024). "Elevated levels of circulating FABP4 in humans are linked to insulin resistance and metabolic syndrome." (PMID 39527497, 2024). "We also reported a significant association between FABP4 and increased insulin levels, a marker for insulin resistance." (PMID 38731797, 2024). "Fatty acid binding protein 4 (FABP4) is a lipid chaperone that contributes to insulin resistance, with high circulating levels of FABP4 being associated with type II diabetes." (PMID 37514127, 2023). "FABP4 has been implicated in the regulation of insulin resistance in mice, and in the regulation of neonatal glucose homeostasis in humans." (PMID 37274820, 2023). "FABP4 is mostly expressed in macrophages and adipocytes, and it has been strongly associated with the development of insulin resistance and atherosclerosis in association with low-grade inflammation." (PMID 37255976, 2023). "Cytoplasmic fatty acid binding protein 4 (FABP4) induces insulin resistance by upregulating glucose production, and high circulating levels of FABP4 independently predict cardiometabolic risk and the risk of type 2 diabetes and breast cancer." (PMID 35954428, 2022). "It has been confirmed that FABP4-deficient mice produces less insulin and shows reduced insulin resistance." (PMID 36060264, 2022). "FABP4 contributes to the development of a variety of pathological conditions associated with the metabolic syndrome cluster such as insulin resistance, obesity, hypertension, heart failure, and atherosclerosis." (PMID 35955575, 2022). "Plasma FABP4 levels in the first and second trimesters were positively associated with fasting insulin and homeostasis model assessment for insulin resistance (HOMA-IR) in the second trimester (both P < 0.001)." (PMID 34368366, 2021). "We performed linear regression to analyze the association of plasma FABP4 concentrations with insulin resistance." (PMID 34368366, 2021). "Human studies have associated elevated circulating FABP4 levels with obesity, insulin resistance, type 2 diabetes." (PMID 34621244, 2021). "FABP4 levels in the first and second trimesters were associated with higher levels of insulin resistance and greater risk of GDM, after controlling for dietary intake, physical activity, and other possible confounders." (PMID 34368366, 2021). "It has been shown that FABP4 deficiency ameliorates insulin resistance and prevents atherosclerosis in apolipoprotein E-deficient mice." (PMID 34621244, 2021). "Targeting Fabp4 with an inhibitor can significantly improve insulin resistance in leptin-deficient ob/ob mice." (PMID 33603666, 2020). "Unfavorable associations between FABP 4 and insulin resistance, diabetes mellitus, gestational diabetes, and the metabolic syndrome, have been reported and FABP4 is further more associated with atherosclerosis and cardiovascular diseases." (PMID 32727561, 2020).